IL10 (interleukin 10)
Diseases named in the same sentence as IL10 in open-access papers (continued):
Sharing a sentence is not in itself a finding about the gene and the disease.
colon carcinoma (129 papers, 2009 to 2025). "The protective role of IL-10 in preventing endogenous tumor development was initially identified in IL-10-deficient (IL-10−/−) mice, which spontaneously developed colon carcinoma." (PMID 40149345, 2025). "Overall, our findings indicated that strong interconnections among the 282 MDGs in colon cancers, with IL-10 and FGF2 acting as core genes that are closely linked to tumor angiogenesis and anti-tumor immune response." (PMID 38327746, 2024). "The knockout of IL-10 in mice causes Th1- or Th17-type chronic inflammation and results in intestinal inflammation and colon cancer; therefore, mice have been used as one of the best animal models of IBD." (PMID 34835369, 2021). "Aicda deficiency was previously reported to decrease inflammation-associated colon cancer in mice, based on the observation that adenocarcinoma had developed in 6 of 22 Il10-/- mice vs. 1 of 23 Il10-/-Aicda-/- mice by ~1 year of age (p = 0.05;)." (PMID 32941525, 2020). "IL-10 permits malignant cells escaping from cell-mediated immune defenses, and is associated with poor prognosis in colon cancer." (PMID 27531897, 2016). "By using interleukin 10 (IL-10) deficient mice as a model, recent studies have shown that Enterococcus faecalis can causes intestinal inflammation and colon cancer during long-term colonization." (PMID 26317438, 2015). "The main objective of our research was to improve the effectiveness of dendritic cell (DC)-based immunotherapy or chemoimmunotherapy composed of cyclophosphamide (CY) and DCs by application of lentivectors encoding shRNA specific to IL-10 (shIL10 LVs) in murine colon carcinoma MC38 model." (PMID 29954431, 2018). "Negative regulators of UC-associated colon cancer have been reported to be IL-10 and TGF-β." (PMID 28621756, 2017). "Furthermore, black raspberries inhibited colonic ulceration associated with colon cancer in interleukin-10 (IL-10) knock-out mouse by suppressing the nuclear translocation of β-catenin." (PMID 26840292, 2016). "IL-10 deficient mice colonized with either Escherichia coli (E. coli) or Enterococcus faecalis develop colon inflammation, but only the mice receiving E. coli developed colon tumors." (PMID 27350830, 2016). "UdF at a concentration of 200 μg/mL significantly reduced the release of IL-1β by cancer cells after a 24 h incubation, but none of the tested extracts affected the release of IL-6 and IL-10 in human colon tumor cells." (PMID 39519642, 2024). "To pinpoint the role of IL-10 in CRC-derived lung metastasis formation, we injected MC38 colon cancer cells i.v. in Il10-/- and wild type (Wt) mice, and assessed the lung metastatic burden 21 days later." (PMID 39681594, 2024). "Reprogramming the colon cancer tumor environment by silencing IL-10 expression resulted in dendritic-cell-dependent activation of the antitumor response." (PMID 36678874, 2023). "In colon cancer, ceramide blocks cell proliferation and migration through the downregulation of IL-10, STAT3 and NF-kB expression." (PMID 38203299, 2023). "They found that the levels of IL-10 and arginase-1 increased, indicating that the colon cancer cells were involved in the M2 polarization of THP-1, which was also confirmed by using the EGFR antibody mAb225 and the PI3K inhibitor LY294002." (PMID 36709284, 2023). "IL-10 exhibits a role in colon cancer progression as increased levels of IL-10 facilitated liver metastasis in a mouse model." (PMID 36678874, 2023). "IL-10 is also an angiogenic factor highly correlated with VEGF in colon cancer (r = 0.749, p = 0.009), as IL-10 induces VEGF expression dose-dependently." (PMID 38049552, 2023). "In this study, analysis of the Creatinine, protein carbonyl, 8-OHdG, VEGF, S.O.D., G.S.H., C.A.T., NO, MMP-9 Inhibitor, and IL-10 was carried out to investigate the nickel-induced biochemical changes in colon cancer cells." (PMID 38049552, 2023).
colon carcinoma (continued). "In the present study, Fe3O4-NPs + 5-FU treatment significantly reduced the IL-10 release of colon cancer cells." (PMID 36678874, 2023). "Colon tumor formation in AOM-treated germ-free IL10−/− mice is greatly abrogated compared to conventional AOM-treated IL10−/− mice due to the impaired inflammatory response." (PMID 35885015, 2022). "IL8 and IL10 mRNA levels were difficult to compare due to their low levels in the colon cancer cells." (PMID 35058516, 2022). "In this regard it is pertinent to recall an elegant study from Dr. Egilmez's group, where they showed that enhancing gut barrier integrity by combination treatment with IL-10 and IL-12 sensitizes colon cancer to immunotherapy." (PMID 35910798, 2022). "In a mouse model of colon cancer, angiotensin II receptor blockers (ARBs) significantly reduced inhibitory T cells and a variety of immunosuppressive factors, including IL-6, IL-10, and VEGF." (PMID 34671200, 2021). "LPEPS oral administration significantly down-regulated pro-inflammatory factors (IL-8, TNF-α, and IL-1β) and up-regulated anti-inflammatory factor (IL-10) levels in the serum of AOM/DSS-induced colon cancer mice." (PMID 34945611, 2021). "IL-10, an anti-inflammatory cytokine that is overexpressed in colon cancer, plays an important role in the progression and metastasis of colon cancer and is considered to be an independent prognostic biomarker of surgical results and recurrences." (PMID 32104586, 2020). "Collectively, these data show that enterohepatic Helicobacter species can trigger sustained inflammation and dysbiosis in IL10−/− mice that leads to the development of colon tumors." (PMID 32286276, 2020). "Bioactivity of hIL-22 was confirmed by the secretion of interleukin 10 (IL-10) from the colon cancer derived epithelial cell line Colo205 and the secretion of Regenerating islet-derived protein 3 alpha (Reg3α) from human jejunal enteroids." (PMID 32582668, 2020). "Genes containing variants uniquely associated only with sub-site risk plus raw P-values < 0.01 comprised rs12124257 in PTGS2 for colon cancer and 4 SNPs in IL10 for rectal cancer." (PMID 31027226, 2019). "Increased numbers of IL-10 and M2 macrophages increase the proliferation and malignancy of colon tumours by inhibiting the activity of natural killer cells and dendritic cells." (PMID 30626010, 2019). "Mechanistically, PKN2 suppresses the expression of IL4 and IL10 from colon cancer cells by inhibiting Erk1/2 phosphorylation, which is required for phosphorylation and binding of CREB and Elk-1 to the promoters of IL4 and IL10." (PMID 29368606, 2018). "Both secreted and anchored mouse IL-22 produced by Lactobacillus was biologically active, as determined by its ability to induce IL-10 secretion in the Colo 205 human colon cancer cell line." (PMID 28830549, 2017). "High IL-10 levels have shown to be secreted from colon cancer cells to promote M2 macrophage differentiation." (PMID 28410235, 2017). "Tregs can be induced in the spleen, TDLN, and tumor tissue by increasing myeloid-derived suppressor cells in IL-10-knockout mice bearing MC38 colon carcinoma cells." (PMID 27075020, 2016). "Recently, HuIL-26 was functionally characterized, and His-HuIL-26 was shown to induce IL-10 and IL-8 in the Colo-205 colon cancer cell line and IL-8 in the Lovo colon cancer and HaCaT cell lines." (PMID 27312894, 2016). "In preliminary studies we found significantly higher levels of both pro–inflammatory cytokines (TNF–alpha, IL–6, IL–8) and anti–inflammatory cytokine IL–10 in colon cancer patients as compared to healthy subjects (unpublished observations)." (PMID 21254741, 2010). "IL-1β, IL-6, and IL-10 responses have been exhaustively investigated, particularly in their connection with tumor growth and metastatic spread in colon cancer resection." (PMID 19309495, 2009).
colon carcinoma (continued). "This relationship has been reported in some studies on colon carcinoma, where they suggest that in certain colon carcinoma cells, the production of IL-10 derived from the tumor is directly regulated by the systemic or local production of pro-inflammatory cytokines, such as IL-6 and IFN-γ." (PMID 40722593, 2025). "Therefore, we aimed to assess radiation quality effects on colonic inflammation, colon cancer incidence, and associated signaling events using an in-vivo CAC model i.e., Il10-/- mice." (PMID 36584137, 2022). "In our experimental model, IL-10 was decreased in colon tumours." (PMID 30626010, 2019). "IL-10 also reduced wnt gene methylation, and thereby inhibits colon cancer incidence." (PMID 29467412, 2018). "Although IL-10 is an anti-inflammatory cytokine and exhibits various immunosuppressive effects in vivo, it has been demonstrated that some colon cancer cells (for example, HT-29) can produce IL-10 themselves, resulting in tumors escaping the immune system’s defenses." (PMID 29162930, 2017). "In our experimental study it was not possible to associate the effect of fructans in colon cancer with the role of microorganisms in the small intestine; however, we studied the possible action mechanism involved in TNFα and IL-10 concentration." (PMID 28293641, 2017). "Mice which are deficient in both IL-10 and AID do not develop colon cancer, whereas IL-10-deficient mice develop spontaneous colon cancers." (PMID 27350830, 2016). "Peritoneal fluids collected at surgery initiation and after surgery were evaluated for their effect on migration potential of human colon cancer cells using an in vitro scratch assay and on TNF-α, IL-1β, IL-6, and IL-10 levels using bead-based fluorokine-linked multianalyte profiling." (PMID 26819599, 2016). "An up-regulated IL-10 was also found in AMSCs co-cultured with colon cancer cells in this study." (PMID 26060426, 2015). "IL-6 induced a STAT3-mediated IL-10 production in colon tumor cells is also reported." (PMID 26556872, 2015). "In colon cancer, although there is discussion in the literature, IL-10 may be used as therapy once it could counter-act the action of pro-inflammatory cytokines that cause chronic inflammation leading to cancer." (PMID 20525400, 2010). "Its protective effects against human colon cancer cells involve inhibition of cell differentiation, promotion of cell-cycle arrest and apoptosis, modulation of histone acetylation, and decrease of pro-inflammatory factors with an increase in the anti-inflammatory cytokine interleukin 10 (IL-10)." (PMID 36982144, 2023). "In the present study, we attempted to find out whether water-soluble polysaccharide isolated from A. heterophyllus can influence the viability of human colon carcinoma cells and change pro- (IL-1β, IL-6) and anti-inflammatory (IL-10) cytokines and nitric oxide (NO) produced by them." (PMID 31947694, 2020). "Thus, in colon cancer patients infected with F. nucleatum, an important increase on TNF-α and IL-10 expression levels have been shown in adenomas, a precursor lesion of colon cancer; while into tumor, IL-6 and IL-8 increased levels were induced by F. nucleatum." (PMID 31662752, 2019). "Interestingly though, frequencies of IL-10-producing Treg were lower in the tumor compared to unaffected colon tissue, suggestive of an imbalance in the immune homeostasis in the tumor, as previously indicated in a mouse model of hereditary colon cancer." (PMID 30651930, 2018). "IL-10 has been thought to be predominately immunosuppressive and thus tumor-promoting, but recent work has provided evidence for IL-10 mediated reduction in tumor growth and metastasis by preventing inflammatory cytokine production in mice transplanted with colon cancer cells." (PMID 28854209, 2017). "In the same study, mice with colon cancer treated with berberine combined with probiotics exhibited reduced IL-17 and IFN-γ levels and increased IL-10 in lung tissue." (PMID 41305617, 2025).
colon carcinoma (continued). "In colon cancer, the GABA-A receptor antagonist picrotoxin significantly reduces IL10–secreting macrophages and restores effector T cell activity, further illustrating the potential of modulating TAMs to boost anti-tumor immunity." (PMID 41019045, 2025). "IL-10 promotes immune suppression in TME, but surprisingly, the reduction predicts poor outcomes in lung and colon cancer." (PMID 36851213, 2023). "Accordingly, macrophages have effect on colon tumor cells by IL-6 production and by activating STAT3 signaling pathway stimulate the production of IL-10." (PMID 35410210, 2022). "For instance, CD115+Gr-1+ M-MDSCs secrete IL-10 and TGF-β in a colon-carcinoma model and induce the differentiation of Foxp3+ Treg in vitro and in vivo in an IL-10- and IFNγ-dependent manner." (PMID 34203451, 2021). "The expression levels of CD4+ T cells, CD8+ T cells, and IFN-γ were down-regulated, whereas those of IL-10 and TGF-β1 were up-regulated in liver metastasis from colon cancer in mice." (PMID 32104586, 2020). "This study showed that the expression of CD4+ T cells, CD8+ T cells, and IFN-γ was down-regulated, while that of IL-10 and TGF-β1 was up-regulated in liver metastases from colon cancers in mice." (PMID 32104586, 2020). "We investigated the expression of IL-10 and TGF-β1 in liver tissue during liver metastasis of colon cancer." (PMID 32104586, 2020). "At the gene level, the interaction P-values of <0.05 were observed for CYP27B1 and GC (vitamin D metabolism) and IL10 (inflammation) for CRC and colon cancer." (PMID 31434255, 2019). "This therapy is associated with enhanced CX3CL1 levels in human colon cancers, leading to the recruitment of non-classical monocytes to the vascular bed of the tumor, where they promote accumulation of neutrophils and immune suppression through IL-10 secretion." (PMID 30930117, 2019). "Given the anti-tumor roles of IL-10 and TGF-β in early stage colon cancer development, we concluded that CXCR3 inhibits early stage colorectal tumorigenesis by attracting both CTLs and Treg cells." (PMID 31775909, 2019). "Similar observations were presented in our previous publication, where we reported the antitumor effects of anti-IL-10 Abs applied in combination with CY and DC-based vaccines used in therapy of MC38 colon carcinoma." (PMID 29954431, 2018). "Significantly decreased IL4 and IL10 levels were found in PKN2 overexpression colon cancer cells, while profoundly increased IL4 and IL10 expression was detected in PKN2-depleted cells." (PMID 29368606, 2018). "Therefore, the higher IL-1β plasma concentrations and lower IL-10 plasma levels in obese animals found in this study may contribute to a suppression of NK cell killing activity against tumor cells and thereby the increased colon cancer incidence in obese rats." (PMID 28357137, 2017). "Vice versa, colon cancer cells were able to induce secretion of cytokines (TNFα, IL10, IFNγ) and metastasis-related factors (VEGFC, MMPs) in MSC via activation of Wnt signaling which in turn resulted in activation of Wnt pathways in colon cancer cells." (PMID 27608835, 2016). "The increase in colon cancer cell migration capacity correlated with increased levels of peritoneal TNF-α and IL-10." (PMID 26819599, 2016). "Treatment with conditioned medium of colon cancer cells increased macrophage expression of the M2-related markers arginase-1 (Arg1), CCL17, CCL22, IL-10 and IL-4." (PMID 27683110, 2016). "Noteworthy, an increased expression of FGF-10, VEGFC, IL-10 and TNFα of AMSCs was found to be along with an elevated EMT gene expression of colon cancer cells in the co-culture model in this study." (PMID 26060426, 2015). "C-reactive protein (CRP), albumin, IL-1α, IL-1β, IL-6, IL-8, IL-10, TNF-α, midkine, VEGF-A, VEGF-C, leptin, adiponectin, and ghrelin serum levels are studied in 126 colon cancer patients and 36 healthy subjects." (PMID 20920199, 2010).
colon carcinoma (continued). "SYBR Green qPCR showed that IL10 and IL12 mRNAs were barely expressed and IL2 mRNA was low, whereas the other ILs were expressed in similar levels to TTP, which were several fold higher than IL2 mRNA in the human colon cancer cells." (PMID 37705049, 2023). "When FJX1 was knocked down in colon cancer cells, the expression of TGFB1 and IL-10 also decreased, suggesting that FJX1 may affect the polarization of macrophages and thus the tumor microenvironment." (PMID 37324001, 2023). "SYBR Green qPCR showed that IL10 and IL12 mRNAs were barely expressed and IL2 mRNA was low, whereas TTP and the other ILs were expressed in similar levels, which were several fold higher than IL2 mRNA in the human colon cancer cells." (PMID 33723275, 2021). "Furthermore, our previous research indicated that the expression of IL-10 and TGF-β1 increases with an increase in the number of colon-cancer cells in the circulation." (PMID 32104586, 2020). "Lactobacillus acidophilus EPS can inhibit the growth of Caco-2 colon cancer cells while EPS from L. gasseri can induce apoptosis in cervical tumor cells, also decreasing the production of TNF-α and increasing the IL-10 production thus controlling inflammation." (PMID 33193180, 2020). "An anti-inflammatory role of IL-10 has been demonstrated in mice lacking the IL-10 gene, wherein colonic inflammation spontaneously develops into colon cancer." (PMID 29662489, 2018). "Moreover, peritoneal liquids harvested after colectomy–from cancer and non-cancer conditions–induced the in vitro migration capacity of colon cancer cell lines, and this effect correlated with increased levels of TNF-α and IL-10 in the samples." (PMID 29462209, 2018). "Colon cancer migration capacity was partly correlated with TNF-α and IL-10." (PMID 26819599, 2016). "In addition, O. splanchnicus showed a significant positive correlation with MUC2, ZO-1, Claudin, and IL-10, and a significant negative correlation with colonic tumor numbers, tumor volumes, advanced colonic lesions, TNF-α, and IL-1β." (PMID 39924893, 2025). "Additionally, previous research revealed that probiotics Clostridium butyricum could similarly increase the expression of the IL-10 and HSP-70 in weaning rex rabbits and colon cancer HT-29 cells." (PMID 35509308, 2022). "Similarly, co-culture of non-stimulated macrophages with NO-producing colon cancer cells led to an increase in IL-6 levels and significantly decreased IL-10 secretion." (PMID 35660630, 2022). "The expression of M2-like macrophage markers Arg1, MRC1 and IL-10, CCL17, and CCL22 were down-regulated, and the expression of M1-like macrophage markers iNOS, IL-12, and TNFa were induced by cetuximab in modeled TAMs, treated with CM of colon cancer cells in vitro." (PMID 34209679, 2021). "Similarly, the number of colonic tumors in DKO mice increased tremendously compared to single KO mice under SPF conditions (P = .025 compared to MSH2loxP/loxP Vil‐cre and P = .032 compared to IL‐10−/− mice)." (PMID 32350866, 2020). "In addition, WSP limited the amount of IL-10 detected in HT29 cells isolated from an early stage of tumor development and increased the amount of this cytokine released by SW620 cells obtained from a colon tumor." (PMID 31947694, 2020). "Our results clearly demonstrated that low-dose CTX selectively suppressed the number of IL-10- and TGF-β1-positive cells, increased the number of conventional CD4+ and CD8+ T cells in the spleen, and efficiently inhibited liver metastasis of murine CT26 colon-cancer cells." (PMID 32104586, 2020). "Nevertheless, polyI:C did not induce TNFα, IL-1β, IL10 and IL-12p40 in HCC and colon cancer cell lines tested." (PMID 28427199, 2017).
colon carcinoma (continued). "However, our study found a negative correlation between Lachnospiraceae UCG010 id.11330 and IL-10, suggesting that Lachnospiraceae UCG010 id.11330 does not mediate colon cancer through IL-10." (PMID 38562480, 2024).